XRCC6 (X-ray repair cross complementing 6)
Diseases named in the same sentence as XRCC6 in open-access papers (continued):
Sharing a sentence is not in itself a finding about the gene and the disease.
cancer (continued). "Moreover, gene–environment and gene–gene interaction analyses, as well as haplotype analysis should be carried out to clarify the role of the XRCC6 genes in cancer." (PMID 25569644, 2015). "Systematic review of association between XRCC6 polymorphisms and cancer risk is lacking, and the role of XRCC6 in the etiology of cancer is still equivocal." (PMID 25569644, 2015). "Notably, TEX10 might regulate carcinoma cell proliferating process and metastasis via XRCC6, thereby controlling the signaling of Wnt/β-catenin and DNA repair channel." (PMID 34966825, 2021). "The results provided evidences that the SNPs in XRCC6 promoter region might associate with the cancer risks, while SNPs in the XRCC6 intron might not." (PMID 25569644, 2015). "The results provided evidences that the SNPs in XRCC6 promoter region might associate with the cancer risks, while SNP in the XRCC6 intron might not." (PMID 25569644, 2015). "In addition, the XRCC6 promoter SNPs might play different roles in various cancers, indicating that XRCC6 gene may have different roles in different cancer development, and different mechanisms promote the development of various tumors." (PMID 25569644, 2015). "However, there was no obvious association between XRCC6 polymorphisms and risks of some “other cancer”." (PMID 25569644, 2015). "Supporting these results, with the exception of XRCC6, all genes coding for “classical” biomarkers of DNA repair activation were significantly more expressed in HPV-related cancers." (PMID 36793865, 2023). "TAZ is a transcriptional coactivator upregulated in different types of cancer; its overexpression stimulates the expression of genes involved in NHEJ, such as TP53BP1 (53BP1), PRKDC (DNA-PKCs), and XRCC6 (Ku70), contributing to the radioresistant phenotype." (PMID 34900673, 2021). "Upon UV exposure, interaction of FOXL2 with both XRCC5 and XRCC6 was significantly diminished in KGN cells, and this effect was consistently observed in other types of cancer cells." (PMID 32332759, 2020). "Taking into consideration the role of XRCC6 and its relevance in maintaining DNA homeostasis, it is not surprising that mutations in this gene may be associated with increased DNA damage and therefore increased aggressiveness, as it has already been shown in other cancers." (PMID 32872534, 2020).
tumor (89 papers, 2000 to 2025). "Each of these XRCC6 polymorphisms was verified as affecting overall tumor risk in a systemic review and meta-analysis." (PMID 28684677, 2017). "We carried out a meta-analysis on all updated published case–control studies to estimate the overall tumor risk of XRCC6 polymorphisms in Asian and European population and to investigate heterogeneity between the individual studies as well as the existence of potential publication bias." (PMID 25569644, 2015). "Gene chip analysis combined with experimental verification has confirmed that PARP6 inhibits XRCC6 expression by inducing its degradation, thereby suppressing the Wnt/β‐catenin pathway, which contributes to tumor suppression in HCC." (PMID 40904702, 2025). "Functional assays demonstrated that the knockdown of XRCC6 led to decreased cell proliferation, whereas its overexpression alleviated DNA damage, highlighting its significance in tumor biology and its potential therapeutic applications." (PMID 39769336, 2024). "XRCC6 was observed to be significantly upregulated in tumor tissues from both the TCGA-LUAD and five GEO datasets." (PMID 39769336, 2024). "Univariate Cox analysis showed that the tumor stage, XRCC4, XRCC5, and XRCC6 were potential risk factors for the OS in patients with LUAD, while no such statistically significant genes were found in patients with LUSC (P < 0.05)." (PMID 34486486, 2021). "Recent evidences have shown that XRCC6 has a close participation in tumor appearance and growth and has great potential as an anticarcinoma drug candidate." (PMID 34966825, 2021). "Statistically significant differences were observed in the patients with LUAD in the XRCC5 and XRCC6 groups (P < 0.05), with a positive correlation between the tumor stage and gene expression." (PMID 34486486, 2021). "In conclusion, these findings indicate that XRCC6 exerts tumor-promoting effects for OS through β-catenin/Wnt signaling pathway." (PMID 27455247, 2016). "Further investigation revealed that the β-catenin/Wnt signaling pathway played an important role in the tumor-promoting effect of XRCC6." (PMID 27455247, 2016). "We found that XRCC6 expression was significantly up-regulated in tumor tissue samples (60%) compared to the controls." (PMID 27455247, 2016). "Recent studies revealed that XRCC6 is a regulator of the β-catenin/Wnt signaling pathway in several tumor types." (PMID 27455247, 2016). "High expression of XRCC6 correlated positively with clinical stage (p < 0.05) and tumor size (p < 0.05)." (PMID 27455247, 2016). "XRCC6 expression levels were negatively related to gender, age, anatomic location, tumor necrosis rate, or degree of malignancy." (PMID 27455247, 2016). "Increasing evidences show that XRCC6 (X-ray repair complementing defective repair in Chinese hamster cells 6) was upregulated and involved in tumor growth in several tumor types." (PMID 27455247, 2016). "Immunohistochemistry was performed for tumor and skin tissues according to the standard procedure using the following primary antibodies: XRCC6 (ab92450; Abcam), LIG4 (ab193353; Abcam), PARP1 (ab191217; Abcam), DNA-PK (#38168; Cell Signaling) and XRCC5 (WH0007520M2; Sigma-Aldrich)." (PMID 38654216, 2024). "XRCC6 was reported to have tumor-promoting effect via Signaling of Wnt/β-catenin channel." (PMID 34966825, 2021). "High expression of XRCC6 was correlated with clinical stage and tumor size in OS." (PMID 27455247, 2016). "In addition, we found that the expression of XRCC6 was correlated with OS Ennecking stage and tumor size according to IHC staining." (PMID 27455247, 2016). "The upregulation of XRCC6 has been reported in several different tumor types." (PMID 27455247, 2016). "Immunohistochemical revealed a notably decrease in protein levels of XRCC6 and 53BP1 in CNOT7 knockdown transplanted tumor." (PMID 41249119, 2025).
tumor (continued). "Comet assay showed that XRCC6 knockdown significantly increased tail length in CNOT7 overexpression cells, a marker of DNA damage, indicating that the tumor cells experienced more severe DNA damage." (PMID 41249119, 2025). "HNSCC: SNHG1 inhibition ↑PARP6 → suppresses tumor growth/migration; HCC: Low PARP6 → HDM2‐mediated XRCC6 degradation → ↑Wnt signaling → promotes progression." (PMID 40904702, 2025). "PRKDC, XRCC6, XRCC5 and PARP1 were significantly downregulated in tumor tissue of mice treated with ESCs and ESC-CM compared with those of mice treated with PBS." (PMID 38654216, 2024). "This analysis revealed significant upregulation of five genes, (XRCC6, XRCC4, PRKDC, XRCC4, and PAXX) and downregulation of two (LIG4 and NHEJ1) NHEJ pathway genes, in tumor tissues compared to the normal tissues." (PMID 33195430, 2020). "We also analyzed the relationship of NHEJ pathway-related genes expression and tumor metastasis of UVM patients in a BioStudies database and found that expression of XRCC6, PRKDC and PARP1 was significantly higher in patients with metastasis than in those without metastasis." (PMID 38654216, 2024). "Interestingly, most CIDGS-related genes, such as XRCC6, ST13, PES1, EFHD2, APOL2, ACTR2, and CDCP1, were markedly upregulated in HNSCC tumor samples, whereas several other genes, such as MARCO, MRC1, and CD83, were upregulated in healthy samples." (PMID 38666027, 2024). "Transcriptome analysis suggests the enhanced DSB repair in tumor cells in the OB can be attributed to an increased expression of a group of genes (MRE11, XRCC5, XRCC6 and PRKDC) essential to the NHEJ pathway of DSB repair, which is a critical determinant of radiosensitivity." (PMID 36482431, 2022). "Consistent with the Oncomine analysis, comparison of all available normal (n = 41) and tumor tissues (n = 469) revealed overexpression of XRCC6, XRCC5, PRKDC, XRCC4, and PAXX in tumors compared to normal tissues, while LIG4 and NHEJ1 displayed lower expression in the tumor tissues." (PMID 33195430, 2020). "Additionally, the combination of STL127705, an inhibitor of the XRCC6/XRCC5 heterodimer, with radiotherapy notably suppressed tumor growth in patient-derived xenograft (PDX) and cell line mouse transplant tumor models, especially in the context of CNOT7 deficiency." (PMID 41249119, 2025). "Furthermore, the overexpression pattern is more robust for XRCC5 as observed in paired normal and tumor tissue comparison, while XRCC6 did not exhibit significant difference." (PMID 33195430, 2020). "Deletion of XRCC6 in mice leads to premature aging without an increased rate of neoplasm." (PMID 29170628, 2017). "Comparison of the methylation levels in LUAD tumor tissues with those in normal tissues identified three relevant methylation sites each in XRCC4 and XRCC5 (P < 0.05), whereas no such methylation sites were found in XRCC6 (P < 0.05)." (PMID 34486486, 2021). "Interestingly, in contrast to Oncomine analysis, XRCC6 and XRCC4 did not display differential expression between paired normal and tumor tissues (respectively)." (PMID 33195430, 2020). "In addition, multivariate Cox analysis demonstrated that the tumor stage, XRCC4, XRCC5, and XRCC6 could predict the tumor prognosis independent of other factors for the OS in patients with LUAD (P < 0.05)." (PMID 34486486, 2021).
infection (19 papers, 2011 to 2025). The state of being infected such as from the introduction of a foreign agent such as serum, vaccine, antigenic substance or organism. "For example, very elegant work by Jill Dembowski and Neal DeLuca using EdU-labeled viral genomes followed by click-chemistry demonstrated an association of several DDR proteins including 53BP1, PARP1, PARP14, MRE11A, and Ku70(XRCC6) with HSV-1 DNA at early time points post infection." (PMID 31500286, 2019).
neurodegenerative disease (3 papers, 2015 to 2022). A disorder of the central nervous system characterized by gradual and progressive loss of neural tissue and neurologic function. "The other five genes, bound by Tau under HS conditions (as also Grm5), were chosen according to their implication in neurodegenerative diseases (Trex1, Dlg2, Dlg1, Xrcc6, Eif2a)." (PMID 30321409, 2018).
neurological disease (2 papers, 2012 to 2021). "Ntrk3, adenylate cyclase activating polypeptide 1 receptor 1 (Adcyap1r1), E2F transcription factor 1 (E2f1) and X-ray repair in Chinese hamster cells 6 (Xrcc6) were represented within the “neurological disease” pathway." (PMID 22934110, 2012).
XRCC6 also shares sentences with these, for which no sentence is quoted: glioma (13 papers); viral infection (10); glioblastoma (8); oral cancer (8); cervical carcinoma (7); pancreatic cancer (7); gastric cancer (5); pterygium (4); chronic myeloid leukemia (3); colitis (3); Fanconi anemia (3); fibrosis (3); Huntington disease (3); Immunodeficiency (3); medulloblastoma (3); multiple myeloma (3); severe combined immunodeficiency (3); T cell lymphoma (3); Werner syndrome (3); acute lymphoblastic leukemia (2); B cell lymphoma (2); cardiac hypertrophy (2); Emphysema (2); endometrial cancer (2); esophageal cancer (2); esophageal squamous cell carcinoma (2); head and neck cancer (2); head and neck squamous cell carcinoma (2); Hepatitis (2); Hyperglycemia (2).
A further 85 diseases each share a sentence with XRCC6 in 2 papers or fewer.